KIR3DL3 (killer cell immunoglobulin like receptor, three Ig domains and long cytoplasmic tail 3)
Description:
Receptor on natural killer cells. May inhibit the activity of NK cells thus preventing cell lysis.
Synonyms: CD158z; KIR3DL7; KIRC1; KIR44
Gene: Protein-coding gene on chromosome 19 (54,724,442 to 54,736,632, forward strand). Ensembl gene ENSG00000242019.
Subcellular location: Cell membrane
Genetic constraint (gnomAD): Loss-of-function variants: 25 observed, 27.14 expected, observed/expected ratio (o/e) 0.92, 90% interval 0.67 to 1.29. The upper end of that interval is the gene's LOEUF score, 1.29, which puts it in group 5 of 6, group 1 being the genes least tolerant of losing a copy. Missense variants: 612 observed, 450.64 expected, observed/expected ratio (o/e) 1.36, 90% interval 1.27 to 1.45. Synonymous variants: 194 observed, 166.89 expected, observed/expected ratio (o/e) 1.16, 90% interval 1.03 to 1.31.
Homologues: Orthologues: chimpanzee KIR3DL3 (85% identical), macaque KIR3DL2 (81% identical), mouse Kir3dl1 (39% identical), mouse Kir3dl2 (38% identical), rat Kir3dl1 (37% identical), tropical clawed frog xilr1 (18% identical). Paralogues in human: KIR3DL2 (78% identical), KIR3DL1 (76% identical), KIR2DL3 (62% identical), KIR2DL1 (60% identical), KIR2DL4 (52% identical), LILRB3 (38% identical), LILRB1 (37% identical), LILRB2 (36% identical), LILRB5 (34% identical), LILRA6 (32% identical), KIR2DS4 (32% identical), LILRA1 (31% identical), and 13 more.
Diseases named in the same sentence as KIR3DL3 in open-access papers:
KIR3DL3 is named in the same sentence as 14 diseases in open-access papers, as found by Europe PMC text mining. Sharing a sentence is not in itself a finding about the gene and the disease. The quoted sentences say what the papers report.
leukemia (2 papers, 2023 to 2026). A malignant (clonal) hematologic disorder, involving hematopoietic stem cells and characterized by the presence of primitive or atypical myeloid or lymphoid cells in the bone marrow and the blood. "Notably, we found that the allelic polymorphisms of the structure gene KIR3DL3 were associated with the occurrence of leukemia." (PMID 41717357, 2026).
chronic myeloid leukemia (1 paper, 2024). "Additionally, studies have reported that HHLA2 in chronic myeloid leukemia cells interacts with KIR3DL3 in NK cells (inhibitory receptor for HHLA2), leading to the inhibition of NK cell cytotoxicity." (PMID 38951802, 2024).
erythroleukemia (1 paper, 2019). Acute erythroid leukemia characterised by the presence of at least 50% erythroid precursors and at least 20% myeloblasts in the bone marrow. "K562, an erythroleukemia cell line with low surface expression of KIR3DL3, was transfected with miRNA inhibitors for miR-26a-5p, miR-26b-5p and miR-185-5p and in combination (miR-26a/b-5p or miR-26a/b-5p ± 185-5p) leading to elevated KIR3DL3 cell surface expression." (PMID 31405037, 2019).
glioma (1 paper, 2013). A benign or malignant brain and spinal cord tumor that arises from glial cells (astrocytes, oligodendrocytes, ependymal cells). "Our results indicate that alterations of eight out of eleven identified genes might have an important role in pathogenesis of glial tumors, while detected changes in GP2, KCNG2 and KIR3DL3 should be considered as passenger mutations, since these genes are not expressed in glial cells." (PMID 24358143, 2013).
influenza (1 paper, 2014). An acute viral infection of the respiratory tract, occurring in isolated cases, in epidemics, or in pandemics; it is caused by serologically different strains of viruses (influenzaviruses) designated A, B, and C, has a 3-day incubation period, and usually lasts for 3 to 10 days. "NK cell response related genes such as CD247, KIR2DL4, KIR3DL1, KIR3DL3 and KLRB1 were down-regulated only in moderate and severe patients while genes such as KIR2DL1, KIR2DS4 and KIR3DL2 were down-regulated in all three groups of influenza patients." (PMID 25365328, 2014).
peptic ulcer disease (1 paper, 2022). A digestive system disease characterized by discontinuation in the inner lining of the gastrointestinal (GI) tract because of gastric acid secretion or pepsin. "While the vast majority of correlations failed false-discovery-rate correction, we discovered a significant correlation between the KIR3DL3*080 allele and ICD10 K25—peptic ulcer disease (PUD) (Fisher’s exact test, FDR= 0.0429)." (PMID 36002830, 2022).
renal cell carcinoma (1 paper, 2023). "Therapeutics targeting HHLA2 or its inhibitory receptor KIR3DL3 are being developed for solid tumors, including renal cell carcinoma (RCC)." (PMID 37891555, 2023).
teratoma (1 paper, 2024). A non-seminomatous germ cell tumor characterized by the presence of various tissues which correspond to the different germinal layers (endoderm, mesoderm, and ectoderm). "The KIR2DL4*00103, KIR2DL5B, KIR3DL3*00302 effects were significantly increased in patients with teratoma and non-teratoma cases with a larger effect in the former group." (PMID 39050850, 2024).
tumor (14 papers, 2022 to 2025). "KIR3DL3 blockade has been shown to inhibit tumor growth in various humanized mouse models, suggesting its potential as an immunotherapeutic target." (PMID 40255615, 2025). "On the other hand, the binding of HHLA2 and KIR3DL3 leads to the inhibition of T cells and mediates tumor resistance against NK cells." (PMID 38786018, 2024). "HHLA2 supports tumor development by acting as an inhibitory immune checkpoint through binding with KIR3DL3 in NK and T cells." (PMID 36982953, 2023). "HHLA2 and its inhibitory receptor, KIR3DL3, are targets for tumor immunotherapy." (PMID 37891555, 2023). "KIR3DL3 recruits SHP-1 and SHP-2 phosphatases, which attenuate signaling pathways such as ERK1/2, AKT and NF-κB, leading to reduced immune cell activation and function, thereby facilitating tumor immune evasion." (PMID 40255615, 2025). "KIR3DL3, as the second receptor of HHLA2, is mainly expressed in terminal differentiation effector memory CD8+ T cells and CD56dim CD16+ NK cells, which mediates co-inhibition of CD8+ T cells and NK cells and induces HHLA2+ tumor tolerance against tumor killing." (PMID 36003385, 2022).
cancer (6 papers, 2022 to 2025). A tumor composed of atypical neoplastic, often pleomorphic cells that invade other tissues. "We identified non-synonymous mutations in KIR3DL3 at tMZL21, which played an important role during cancer development." (PMID 39460552, 2024). "There is scarce knowledge in KIR2DL1 and KIR3DL3 association with cancers." (PMID 35652109, 2022). "Targeting the HHLA2/KIR3DL3/TMIGD2 pathway, which we intend to explore in the future work, may be beneficial for cancer treatment and improve clinicopathological conditions such as survival." (PMID 38731979, 2024). "In addition to HLA, KIR3DL3 was more recently discovered as a novel interaction partner for HHLA2 (a immune checkpoint member of the B7 family), which has both immune inhibitory and activating abilities and is expressed in many human cancers." (PMID 36178190, 2022).
KIR3DL3 also shares sentences with these, for which no sentence is quoted: lung carcinoma (2 papers); colorectal cancer (1); Diabetes (1); encephalitis (1).